HIF1A (hypoxia inducible factor 1 subunit alpha)
Diseases named in the same sentence as HIF1A in open-access papers (continued):
Sharing a sentence is not in itself a finding about the gene and the disease.
tumor (continued). "Therefore we used a comprehensive approach to genetically approach to inhibit the pathways in the tumor cells by expression of HIF-1α shRNA and a dominant-negative TβRII, which then were analyzed an in vivo bone metastasis model." (PMID 19727403, 2009). "As expected, we showed a significant association between HIF-1α and VEGF in both ECs and epithelial/tumour cells, as it is known that the HIF-1 complex recognises a consensus hypoxia response element in the promoter of VEGF that mediates hypoxic signals including angiogenesis." (PMID 19623180, 2009). "Thus, we identify a novel molecular regulation mechanism through which miR-20b regulates HIF-1α and VEGF and is regulated by HIF-1α so to keep tumor cells adapting to different oxygen concentrations." (PMID 19893619, 2009). "This may have important implications, as these tumours may respond to compounds directed against HIF-1α or its downstream targets." (PMID 19724277, 2009). "This is supported by studies suggesting hypoxic tumours may respond to Bortezomib and Amphotericin B, which suppress HIF-1α activity by re-enforcing FIH-mediated inhibition of p300 recruitment." (PMID 19724277, 2009). "Ninety-four out of 188 tumours (50%) stained positive for HIF-1α." (PMID 19165203, 2009). "In addition, our results suggest a role for HIF-1α to regulate interactions between tumor cells and other cells in the bone microenvironment, such as endothelial cells." (PMID 19727403, 2009). "HIF-1α expression correlates with increasing tumor grade, invasion, and metastasis." (PMID 19727403, 2009). "Based on our results we hypothesize that HIF-1α could function as a linking transcription factor for LPS-mediated processes along the tumor invasion from the luminal site to the site of deepest penetration." (PMID 18983642, 2008). "It is already known that HIF-1α is one of the key factors regulating cellular O2 homeostasis and its activation represent a key step in angiogenesis and adaptation to hypoxia and thus the vitality of the tumor." (PMID 18173856, 2008). "Due to the fact that intestinal mucosal injury may permit translocation of bacteria and endotoxin, this topological accumulation of the active form of HIF-1α could be of great importance for tumor progression." (PMID 18983642, 2008). "In addition, the production of growth factors in the tumor cells is often controlled by transcriptional regulators, the most prominent of which appears to be HIF-1α." (PMID 18423023, 2008). "The hypoxia-inducible factor-1α (HIF-1α) is linked to cancer through its regulation by RONS; in particular, RONS signalling may account for the high levels of HIF-1α in normoxic areas of tumours." (PMID 18253125, 2008). "Because of the chosen design in this study with comparison of non-metastatic and metastatic colorectal carcinomas with the same grading of differentiation and infiltrating depth, the influence of both essential tumor features on the HIF-1α expression can be excluded." (PMID 18983642, 2008). "Since HIF-1α is the key molecule regulated by tumour hypoxia, HIF-1α deregulation in tumour cells may confer resistance in these cells." (PMID 19014607, 2008). "Importantly, Western blotting of tumor tissues showed markedly decreased HIF-1α expression in ENMD-1198 treated tumors, suggesting that this target is inhibited in vivo." (PMID 18651980, 2008). "In fact, one has to realize that tumor sizes differ significantly among these treatment groups, which per se could affect HIF-1α expression." (PMID 18651980, 2008). "Simultaneously, HIF-1α activation in the dissociated tumor cells could be explained as initiation of a "one way" cascade leading to cell death." (PMID 18983642, 2008). "One interpretation is that high HIF-1α-expressing suboptimally resected tumours are chemoresistant." (PMID 19014607, 2008). "HIF-1α activation in the cohesive tumor cells could be explained as transduction to an adequate adaptative intracellular response to prevent from cell death." (PMID 18983642, 2008).
tumor (continued). "In fact, HIF-1α is involved in tumor progression by promoting genomic instability." (PMID 18983642, 2008). "Importantly, the ability of ENMD-1198 and 2ME2 to inhibit HIF-1α has recently been suggested in preclinical tumor models of solid malignancies." (PMID 18651980, 2008). "This differential regulation might also be determined in individual tumours by the different processes leading to HIF-1α stabilisation (e.g. hypoxia/oncogene/ROS)." (PMID 17179985, 2007). "Our observation that HIF-1α expression is an early feature of gastric carcinogenesis suggests it may play a role in promoting molecular changes that drive tumour formation." (PMID 17179985, 2007). "However, it was noted that tumour cells adjacent to areas of surface ulceration that were peri-necrotic in nature showed increased levels of HIF-1α expression." (PMID 17179985, 2007). "However, studies of HIF-1α expression have been conflicting in several tumour subsites, including cervical, lung and ovarian cancer." (PMID 17179985, 2007). "The lower HIF-1α expression in high-grade CC-RCC could possibly be explained by a progressive switch to HIF-2α response during tumour progression." (PMID 17505508, 2007). "Carbonic anhydrase IX and HIF-1α were expressed in 97 and 88% of all tumours, respectively." (PMID 17505508, 2007). "In the presented work, an upregulation of HIF-1α in tumours over time as their size increased was observed, that may be secondary to an increased hypoxia with tumour growth." (PMID 17342092, 2007). "In univariate analysis and in comparison with tumours not expressing HIF-1α, invasive edge staining was associated with a hazard ratio of 1.6 (95% CI 1.0−2.5) and focally positive staining a hazard ratio of 0.7 (95% CI 0.5−1.2)." (PMID 17179985, 2007). "Although in this study we focused on the effect of VHL inactivation on CXCL12/CXCR4-mediated organ-specific metastases, it is possible that other hypoxia-inducible genes under the control of HIF-1α/VHL pathway may also play a role in tumor metastasis." (PMID 17083723, 2006). "As for TP, HIF-1α protein levels can be raised in tumours due to stimuli other than hypoxia: activation of oncogenes HER2, v-src and H-ras; loss of tumour suppressor gene function such as PTEN and signalling abnormalities such as MAPK." (PMID 16317434, 2006). "As expected, immunoreactivity for HIF-1α was observed in the nuclei of tumour cells." (PMID 16832411, 2006). "Under hypoxic conditions, HIF-1α may inhibit tumor proliferation through p21-mediated cell cycle control, resulting in the selection of cells that are resistant to apoptosis and anti-cancer treatments." (PMID 17166265, 2006). "In the clinically most relevant primary node negative T1/T2 tumours, loss of HIF-1α expression identified a subgroup of high-risk patients." (PMID 16035955, 2005). "Our data show that mitochondrial complex II mutations lead to upregulation of HIF1α targets in human tumor tissue and indicate an additional level of interplay between the SDHB and HIF1α proteins, i.e., a reciprocal effect of HIF1α in modulating components of the mitochondrial complex II." (PMID 16103922, 2005). "CA9 and Hif-1α expression were correlated (primary tumours P=0.005; lymph node metastases P<0.001)." (PMID 16251878, 2005). "The expression of HIF-1α was related with a significantly improved 5-year survival rate (p < 0.01) and a significantly increased disease free period (p = 0.01) independent from nodal status and tumour size." (PMID 16035955, 2005). "The tumor biological significance of increased epithelial HIF-1α and CAIX expression is unclear." (PMID 16168127, 2005). "Also in adenocarcinomas of the breast, diffuse HIF-1α expression was associated with a better survival than hypoxia induced perinecrotic HIF-1α expression." (PMID 16035955, 2005).
tumor (continued). "High tumour cell proliferation involves increased oxygen consumption, leading to oxygen deficiency and hypoxia-modulated gene expression, including activation of vascular endothelial growth factor and CA9 gene transcription by Hif-1α." (PMID 16251878, 2005). "It is therefore possible that different tumour cell lines may demonstrate considerable variation when studying the effects of TP activity upon HIF-1α induction." (PMID 15841086, 2005). "In less than 5% of the cases necrotic areas were seen, and expression of HIF-1α could also be detected in perinecrotic vital tumour cells." (PMID 16035955, 2005). "CA9, DEC-1 and Hif-1α were expressed in, respectively, 38.3, 76.7 and 46.7% of primary tumours." (PMID 16251878, 2005). "Necrosis may be attributable to several factors, but an important factor is likely to be hypoxia and the relation between CA IX and necrosis is consistent with the recently described relation between HIF-1α and prognosis in tumours." (PMID 12671706, 2003). "Mild ischemia during tumor resection causes minimal HIF-1α reduction without functional impact." (PMID 41602837, 2026). "Furthermore, HIF-1α can trigger the synthesis of lincRNA-p21, which stabilizes the protein level of HIF-1α and increases the glycolytic metabolic activity of tumor cells by preventing the ubiquitination and destruction of HIF-1α by interfering with the interaction between VHL and HIF-1α." (PMID 41614928, 2026). "Thus, tumor cells may upregulate HIF‐1α expression by utilizing FAs extorted from nearby adipose tissues, thereby reducing the adjacent adipose tissue volume and promoting cancer progression." (PMID 41160815, 2026). "Under hypoxic conditions, tumor cells control the amount of oxygen that enters their mitochondria to stop ROS formation and enhance fission and mitophagy processes for eliminating damaged mitochondria while HIF‐1α stabilizes to strengthen hypoxic signaling via succinate accumulation." (PMID 41521160, 2026). "Additionally, in vivo experiments using syngeneic transplantation of CT26 cells in mice revealed that combining RSL3 with an HIF-1α inhibitor markedly enhanced tumor suppression and metastasis prevention, concomitant with increased intratumoral infiltration of CD8+ T cells and CD86+ macrophages." (PMID 41945999, 2026). "Instead, tramadol-treated cells showed reduced migratory and metastatic potential, implying that HIF-1α activation alone is insufficient to drive tumor progression and may be counterbalanced by other tramadol-mediated effects, such as cell-cycle arrest and apoptosis induction." (PMID 41526224, 2026). "Indeed, via HIF-1α activation, hypoxia also stimulates the expression in cancer cells of anti-apoptotic, proliferative and neo-angiogenic genes that clearly contribute to enhancing tumor growth and aggressiveness." (PMID 40558563, 2025). "In addition to helping tumor growth, the induction of multiple factors facilitates increased resistance to treatment options, such as chemotherapy and radiation, thereby emphasizing the importance of understanding the role of HIF1α in brain metastasis." (PMID 40806669, 2025). "Furthermore, HIF-1α can regulate immune cell infiltration into the tumor." (PMID 40746883, 2025). "Furthermore, we conducted Kaplan-Meier survival analysis for HIF-1α, which revealed that high HIF-1A expression may promote tumor cell survival and metastasis in hypoxic microenvironments." (PMID 40406267, 2025). "Therefore, we hypothesise that the reduction of C1QBP may cause mitochondrial damage, leading to compromised cellular function and the passive activation of HIF‐1α in tumour cells, ultimately enhancing glycolysis to compensate for the energy deficit." (PMID 39748215, 2025).
tumor (continued). "Notably, the characteristic hypoxic features of HCC further enhanced M2-type polarisation through the HIF-1α-VEGF pathway, leading to a significantly higher percentage of M2-type TAMs in TME, an imbalanced state that is closely associated with tumour immune escape and poor prognosis." (PMID 40495147, 2025). "Further data from preclinical and translational studies also suggest that mTOR inhibition might suppress tumor growth by modulating hypoxia signaling and autophagy through hypoxia-inducible factor 1-alpha (HIF-1α), underscoring a broader biological rationale for its use." (PMID 41002573, 2025). "Furthermore, the changes in tumor cell clustering ability, adhesion strength and cell junction protein expression induced by HIF-1α knockdown could be significantly reversed by the addition of recombinant DSG2." (PMID 41381723, 2025). "Therefore, prior to the design and implementation of effective tumor therapy, it is of great significance to deeply explore the pathological mechanism of HIF-1α expression and develop targeted therapies for it to improve the therapeutic effect and overcome drug resistance." (PMID 39897552, 2025). "Thus, HIF-1α is not only involved in tumor progression and escape from immune surveillance but may also directly affect T cell functionality." (PMID 40963621, 2025). "However, with the removal of sensitive cells at the initial stage of treatment, surviving tumor cells activate prosurvival pathways such as NF‐κB and HIF‐1α through epigenetic modifications (e.g., histone deacetylation), which in turn affects tumor drug resistance." (PMID 40979214, 2025). "Therefore, HIF-1α in tumor cells is stabilized only under hypoxic conditions." (PMID 40709182, 2025). "Molecular alterations associated with the diabetic phenotype, such as abnormalities in insulin signaling, which results in insensitivity to insulin and subsequent hyperinsulinemia, may ultimately favor tumor development through the regulation of HIF-1α, increased glucose uptake, and its utilization." (PMID 39996906, 2025). "Consequently, the administration of exogenous Neu5Ac, which leads to decreased HIF-1α levels under normoxic conditions, may impair fatty acid uptake and storage, thereby compromising the metabolic adaptability of tumor cells." (PMID 41333208, 2025). "Similarly, tumor cells may develop escape mechanisms to minimize the effects of hypoxia-induced factors (such as HIF-1α, fibroblast growth factor, or mesenchymal–epithelial transition signaling pathways)." (PMID 40647409, 2025). "Additionally, addressing tumor hypoxia with HIF-1α inhibitors and combining them with VEGF inhibitors could further optimize immune responses." (PMID 41182416, 2025). "According to the content summarized in this article, after HIF-1α is inhibited, the expression of multiple metalloproteinases is reduced, and the concentrations of sMICA and sMICB are decreased; NK cells in cancer patients are relieved from inhibition and resume their anti-tumor activation." (PMID 40563539, 2025). "Also, these accumulated genetic mutations regulate oncogenic signaling pathways and the activation of transcription factors such as HIF1A, conferring a survival advantage by facilitating rapid cell proliferation and adaptation to the hypoxic tumor microenvironment." (PMID 40089067, 2025). "Under hypoxic conditions, tumor cells exhibit an increased uptake of FAs mediated by the expression of fatty acid binding proteins 3/7 (FABP 3/7) dependent on hypoxia-inducible factor-1α (HIF-1α), a process accompanied by a reduction in de novo fatty acid synthesis." (PMID 40137165, 2025). "Furthermore, the reduction in expression and secretion of angiogenesis-related factors VEGF-A and HIF-1α implies that the combination therapy might also inhibit tumor vascularization." (PMID 39796221, 2025).
tumor (continued). "In addition, hypoxia signaling has a significant impact on the Notch1 and HIF-1α signaling pathways, which influence each other and participate in physiological and pathological processes related to hypoxia, such as angiogenesis and tumor metastasis." (PMID 41162811, 2025). "However, its activation of HIF-1α in the tumor microenvironment may promote tumor progression through mechanisms such as angiogenesis, glycolysis enhancement, and immune evasion." (PMID 41311849, 2025). "Cu can also function as a signaling molecule promoting tumor cell proliferation, invasion, and angiogenesis by activating or inhibiting signaling pathways such as phosphatidyqinositol-3 kinase/protein kinase B, hypoxia inducible factor 1 subunit alpha (HIF-1α), and nuclear factor kappa-B." (PMID 41304721, 2025). "In light of our findings that high HIF1A expression is associated with reduced NK cell activity and tumor dedifferentiation, we propose that targeting HIF1A may serve as a “dual-purpose” strategy: reversing dedifferentiation while restoring immune responsiveness within the tumor microenvironment." (PMID 40552073, 2025). "HIF1α and HIF2α are expressed in different tissues and regulate target genes involved in angiogenesis (like VEGF), cell proliferation and inflammation, epithelial-to-mesenchymal transition, apoptosis, metastasis, and tumor invasion, and their expression is associated with different disease states." (PMID 40995093, 2025). "To investigate whether HIF1α, a principal transcription factor activated under hypoxic conditions within the tumor microenvironment, contributes to the regulation of IL-6 production, we employed siRNA-mediated knockdown of HIF1α in PC-9 cells followed by exposure to hypoxia." (PMID 41254082, 2025). "Therefore, targeting HIF-1α could be a promising strategy to overcome hypoxia and to improve tumor sensitivity to chemotherapy." (PMID 40872479, 2025). "Similarly, decreased expression levels of miR-143-3p in E vs. C could contribute to overexpression of IL-6, HIF-1α and NF-κB p65, as observed in tumor growth." (PMID 41013698, 2025). "Therefore, in our study, HIF-1α was examined in both tumor tissue and microenvironment." (PMID 39996842, 2025). "Recent studies suggest that targeting TAMs-associated pathways, such as the IL-6/interleukin-8 (IL-8) axis or lactate-monocarboxylate transporter-hypoxia-inducible factor 1 alpha (HIF1α) signaling pathway, could reprogram macrophages and disrupt their pro-tumor activities." (PMID 40098971, 2025). "Reduction in HIF-1a may indicate a tumor more amenable to ICI therapy by altering PD-L1 expression." (PMID 41012682, 2025). "Moreover, RUNX2 may support this process by stabilizing and preventing HIF-1α production in tumour cells." (PMID 40806771, 2025). "Furthermore, a decrease in H2O2 levels in cancer cells can lead to inhibition of proliferative pathways, including those regulated by HIF-1α and NF-κB, which may further enhance the anti-tumour effect." (PMID 40943423, 2025). "Furthermore, activation of hypoxia-inducible factor-1α (HIF-1α) observed in our results may reflect IR808-ATIPA’s regulatory effects on the tumor hypoxic microenvironment." (PMID 40831788, 2025). "Hypoxia may also contribute to tumor escape from the immune system affecting the number and functionality of the natural killer cells (NK), T cells, and dendritic cells (DCs) by regulating the expression of HIF-1α." (PMID 40963621, 2025). "Consequently, the hypoxic HIF-1α/VEGF regulatory axis is crucial for tumour progression." (PMID 40806771, 2025). "Finally, HIF1A, a central factor in the cellular response to hypoxia, plays a critical role in tumor growth by promoting angiogenesis and metabolic reprogramming in the hypoxic tumor microenvironment." (PMID 41411347, 2025). "Similarly, miR-186 targets HIF-1α in other neoplasms and downregulates aerobic glycolysis." (PMID 40072059, 2025).